RAC1 (Rac family small GTPase 1)
Diseases named in the same sentence as RAC1 in open-access papers (continued):
Sharing a sentence is not in itself a finding about the gene and the disease.
atherosclerosis (28 papers, 2014 to 2024). A disease characterized by the build-up of fatty material and calcium deposition in the arterial wall resulting in partial or complete occlusion of the arterial lumen. "To do this, we generated mice deficient for RAC1 in macrophages using the Cre-loxP system and induced atherosclerosis to define the consequences of Rac1-deficiency on macrophage function and plaque development." (PMID 32941503, 2020). "Rac1 also regulates a number of cellular processes that are associated with advanced atherosclerosis." (PMID 27442895, 2017). "KALRN genetic variations may lead to endothelial dysfunction and atherosclerosis through influence on the Rac-1 signaling pathway, which is associated with Type 2 diabetic." (PMID 32671063, 2020). "To define whether elevated RAC1 expression in human atherosclerotic plaques may have a biological role in macrophages, we induced atherosclerosis in mice deficient for RAC1 in macrophages and observed fewer macrophages as well as smaller atherosclerotic plaque size." (PMID 32941503, 2020). "Arg-1 metabolizes arginine and ornithine derived from apoptotic cells to produce putrescine, which enhances Dbl/Rac1-mediated engulfment of secondary apoptotic cells, thereby sustaining efferocytosis and promoting regression of atherosclerosis." (PMID 39660125, 2024). "Of special note, RAC1, which has been shown as an interesting link between inflammation and calcification in atherosclerosis, was found to be highly upregulated in 100K ECM MM." (PMID 39596469, 2024). "(C) Macrophages engulf apoptotic cells during efferocytosis and take up arginine and ornithine being converted into putrescine, which strengthens subsequent efferocytosis by increasing Rac1 activation and promotes resolution of atherosclerosis." (PMID 36624476, 2023). "Putrescine strengthens subsequent efferocytosis by increasing Rac1 activation and promotes resolution of atherosclerosis." (PMID 36624476, 2023). "It was also reported that pharmacological inhibition of Rac1 improves endothelial function and attenuates atherosclerosis development in mice." (PMID 35340217, 2022). "Treatment with Rac1 inhibitor elevates endothelial function and reduces atherosclerosis in ApoE knockout mice." (PMID 36185329, 2022). "Rac1b as a constitutively active form of Rac1 is therefore relevant in pathogenesis involving macrophage Rac signaling, such as in the case of atherosclerosis." (PMID 34831028, 2021). "Some studies showed that Rac1 inhibition decreased atherosclerosis in animal models via improved endothelial function." (PMID 34831028, 2021). "Next, the effect of long-term Rac1 GTPase inhibition by LT on atherosclerosis development was tested." (PMID 34422919, 2021). "Prior studies that assessed the role of Rac1 in atherosclerosis progression were carried out using the Watanabe heritable hyperlipidemic (WHHLMI) rabbit model." (PMID 34831028, 2021). "Deficiency of P-Rex1 in mouse macrophages was found to significantly decrease macrophage chemotaxis, superoxide production (SOD), and Rac1 activation in response to chemo-attractants, suggesting the regulatory role of P-Rex1 in atherosclerosis." (PMID 35047576, 2021). "We now provide evidence of reduced macrophage infiltration of atherosclerotic plaques after long-term Rac1 inhibition, further supporting the importance of Rac1 GTPase for monocyte function in vivo and development of atherosclerosis." (PMID 34422919, 2021). "This study used in vitro and in vivo experiments to demonstrate that Vav1/Rac1 signaling promotes the progression of atherosclerosis by affecting the migratory ability of foam cells in atherosclerotic plaques." (PMID 32190703, 2020). "Other studies of the significance of the RhoA and Rac1 prenylation for atherosclerosis development have focused on the role of the unmodified and geranylgeranylated RhoA and Rac1 in the atherosclerosis progression in the rabbit model." (PMID 33379334, 2020).
atherosclerosis (continued). "The issue of farnesylation and geranylgeranylation of RhoA, Rac1, and CDc42 in atherosclerosis is important for the therapeutic use of the lipid-lowering agents, statins, in the prevention and reduction of atherosclerosis." (PMID 33379334, 2020). "NADPH oxidases have also been shown to contribute to atherosclerosis, thereby implicating Rac1 in disease progression." (PMID 27442895, 2017). "Rac1 contributes to the accumulation of SMCs in the inner layer of arteries in atherosclerosis through regulating SMCs' migration." (PMID 27442895, 2017). "This indicates that increased activation of Rac1-PAK signaling can stimulate atherosclerosis, through enhancing the deposition of lipoproteins on vasculature walls." (PMID 27442895, 2017). "In the carotid artery injury model, Ohkawara reported that Rac1 activity is higher in atherosclerosis plaques, and is proportional to the degree of hardening of the arteries." (PMID 24667766, 2014). "Our present data suggest that HMGB-1 activates MT1-MMP through RAGE lead ing to RhoA/Rac1 activation, NF-κB phosphorylation and TF protein upregulation as a pathology of the progression of atherosclerosis and vascular endothelial dysfunction." (PMID 25490770, 2014). "IL-10, in turn, enhances efferocytosis in advanced atherosclerosis via the IL-10/Vav1/Rac1 pathway." (PMID 39660125, 2024). "Indeed, Rac1 has been demonstrated to be a major regulatory determinant of macrophage IL-1β, which in turn is a key mechanism in promoting atherosclerosis calcification." (PMID 39596469, 2024). "In experimental atherosclerosis models, we recently identified a potential mechanism of statin-induced atherosclerotic plaque calcification through inhibition of Rac1 protein isoprenylation and consequent dysregulation of the small GTPase, Rac1." (PMID 37498869, 2023). "In the present work we have used specific inhibitors of Rac1 activity to investigate the role of the GTPase in atherosclerosis using a mouse model and conclude that Rac1 inhibition could indeed be an important therapeutic principle." (PMID 34422919, 2021). "Rac1 is involved in several cardiovascular pathologies, e.g., vascular smooth muscle proliferation, atherosclerosis cardiomyocyte hypertrophy and endothelial dysfunction in hypertension, and is considered a promising therapeutic target in cerebro- and cardiovascular diseases." (PMID 33799511, 2021). "P-Rex1 regulates Rac1 activation and chemotaxis in macrophages, and may be a regulator for atherosclerosis." (PMID 35047576, 2021). "Another prior study evaluated Rac1 in the context of chronic infection with Chlamydophila pneumoniae, which is a Gram-negative bacterium that is associated with asthma and atherosclerosis development." (PMID 34831028, 2021). "To investigate whether Rac1 inhibition in the aortic wall affects atherosclerosis, we assessed atherosclerotic plaque formation in the aortic root of these mice." (PMID 34422919, 2021). "Elevated RAC1 expression in intimal macrophages from human carotid endarterectomies with advanced atherosclerotic lesions prompted us to hypothesize that inhibiting RAC1 could reduce atherosclerosis in vivo." (PMID 32941503, 2020). "Genetic inactivation of RAC1 impaired macrophage function and reduced atherosclerosis in mice, suggesting that drugs targeting RAC1 may be useful in the treatment of atherosclerosis." (PMID 32941503, 2020). "Moreover, we found that RAC1 interacts with actin-binding filamin A. Macrophages expressed increased RAC1 levels in advanced human atherosclerosis." (PMID 32941503, 2020). "Importantly, our results can be utilized to further facilitate the development of effective pharmacological agents that can inhibit RAC1 signaling in macrophages in atherosclerosis-related cardiovascular disorders." (PMID 32941503, 2020).
atherosclerosis (continued). "Additionally, a recent study reported that DOCK4 promotes the internalization of scavenger receptor class B type 1 and LDL transport by activating the RHO GTPase RAC1, which may promote atherosclerosis in endothelial cells." (PMID 36882763, 2023). "Secondly, RAC1 induces actin reorganization during cell membrane ruffling and phagocytosis and inhibition of targeting actin dynamics in BMMs could be a potential target for treating atherosclerosis." (PMID 32941503, 2020). "Recent observations indicate that RAC1 could be a potential target in atherosclerosis." (PMID 32941503, 2020). "A recent study discovered that human atherosclerosis has higher levels of DOCK4 and scavenger receptor class-B type-1 (SR-B1), and DOCK4 activates Rac1 by boosting LDL binding to SR-B1, promoting SR-B1 internalization and transport of LDL." (PMID 36882763, 2023). "In atherosclerosis, activation of HMGB1 and RhoA/Rac1 is closely related to vascular inflammation induced by NF-κB phosphorylation in endothelial cells." (PMID 35674581, 2022). "Moreover, outside of Rac2 deletion leading to progressive atherosclerotic calcification, the relative impact of this Rac1–IL-1β signaling axis in the natural progression of atherosclerosis and/or atherosclerotic calcification in the context of hyperlipidemia remains unclear." (PMID 34831028, 2021). "Our previous study demonstrated that simvastatin inhibited Rac1 and Rac1-dependent NADPH oxidase activity to exert their beneficial effects in atherosclerosis." (PMID 29207644, 2017). "Reports have shown that RhoA, Rac1, and CDC42 play important roles in atherosclerosis." (PMID 36185329, 2022). "Concomitant treatment of cholesterol-fed ApoE−/− mice with LT, the specific synthetic Rac1 inhibitor NSC 23766 or simvastatin comparably reduced aortic Rac1 activity, NADPH oxidase activity, oxidative stress, endothelial dysfunction, atherosclerosis development, and macrophage infiltration." (PMID 34422919, 2021). "In addition to Akt, effectors downstream of PI3K include Ras-related C3 botulinum toxin substrate 1 (Rac1) and Protein kinase Cζ (PKCζ), but of the many of PI3K signaling pathways, the PI3K/Akt pathway is most closely related to atherosclerosis." (PMID 33767629, 2021). "This study is the first to show that lack of RAC1 in macrophages in vivo inhibits aortic plaque size in an in vivo model of atherosclerosis." (PMID 32941503, 2020). "Furthermore, cytoskeletal FLNACT produced by calpain cleavage physically interacted with RAC1 and we have previously shown that lack of FLNA reduces macrophage activity and atherosclerosis." (PMID 32941503, 2020).
Hyperglycemia (28 papers, 2011 to 2025). An increased concentration of glucose in the blood. "We have recently observed that the single nucleotide polymorphisms (SNP) of the RAC1 gene are tightly associated with impaired redox homeostasis, an increased risk of type 2 diabetes, and hyperglycemia." (PMID 36979960, 2023). "Single nucleotide polymorphisms (SNP) in the RAC1 (Rac family small GTPase 1) gene have recently been linked to type 2 diabetes (T2D) and hyperglycemia due to their contribution to impaired redox homeostasis." (PMID 36979960, 2023). "Rac-1 is associated with adiponectin and has a direct connection with hyperglycemia and ß-cell apoptosis." (PMID 28191276, 2017). "In a cardiomyocyte-specific Rac1 knockout model generated by breeding Rac1flox/flox mice with α-MHC-cre mice, deficiency of Rac1 reduced hyperglycemia-induced mitochondrial ROS production and myocardial dysfunction." (PMID 28101515, 2016). "Hyperglycemia also increases H3K9me3 levels and decreases H3K9me2 levels at the Rac1 promoter, activating Rac1 expression, which in turn increases ROS production through the Nox2 pathway, causing mitochondrial damage and retinal lesions." (PMID 40305347, 2025). "The presence of ceramides further intensifies the hyperglycemia-induced activation of the Rac1-Nox2-ROS signaling pathway and leads to increased mitochondrial damage." (PMID 39512998, 2024). "Previous studies showed that hyperglycemia is associated with increased Rac-1/PAK binding and enhanced Rac-1 translocation from the cytosol to the plasma membrane by ROS." (PMID 36831080, 2023). "Hyperglycemia also accelerates Rac1 transcription via dynamic DNA methylation–hydroxymethylation of its promoter." (PMID 36202842, 2022). "Suv39H1-siRNA also attenuates hyperglycemia-induced increase in Rac1 expression, further supporting the role of H3K9me3 at Rac1 promoter in DNA methylation." (PMID 34238980, 2021). "Our results from experimental models of type 1 and type 2 diabetes have shown that hyperglycemia, in a hyperlipidemic milieu further activates Tets and increase in 5hmC levels, aggravating Rac1 transcriptional activation." (PMID 34063353, 2021). "As detailed above, a combination of hyperlipidemia and hyperglycemia further activates Rac1-Nox2 signaling, potentiating and exacerbating ROS production, and accelerating mitochondrial damage." (PMID 34063353, 2021). "Because NADPH oxidase activation is directly related to increased oxidant production induced by hyperglycemia, we evaluated Rac1 activity and gp91phox and p47phox (NADPH subunits) expression." (PMID 26989696, 2016). "In addition, emerging evidence suggests that sustained (constitutive) activation of smgs (e.g., Rac1) culminates in the genesis of islet beta cell dysfunction under the duress of chronic hyperglycemia." (PMID 40710299, 2025). "Hyperglycaemia activates NOXI through PKC-dependent Rac1 activation." (PMID 35918636, 2022). "SUV39H1 is responsible for trimethylation at H3K9 to H3K9me334; our results show that its expression and binding at Rac1 promoter are increased in hyperglycemia, and silencing of Suv39H1 attenuates increase in 5hmC, which is a product of dynamic DNA methylation." (PMID 34238980, 2021). "Regulation of histone methylation enzyme, Suv39H1, by its specific siRNA inhibits hyperglycemia-induced increase in 5hmC at Rac1 promoter and ameliorates increase in Rac1 gene transcripts, implying a close cross-talk between DNA methylation and H3K9 methylation." (PMID 34238980, 2021). "Our data indicated that hyperglycemia-induced Rac1 activation could be mediated by mtROS either directly or via stimulation of RhoA that balanced Rac1-dependent cytoskeleton rearrangements." (PMID 28761623, 2017). "We showed that hyperglycemia mediated the upregulation of NOX4, p47phox and Rac-1 protein levels, which were significantly reduced by GLP-1." (PMID 28808291, 2017).
Hyperglycemia (continued). "Numerous molecular and cellular studies have demonstrated that small GTP-binding proteins, consisting of the Ras and Rho family (RhoA and Rac1), participate in the VSMC mitogenic machinery triggered by hyperglycemia." (PMID 25918730, 2015). "Our findings suggest that: [i] inhibition of Tiam1-Rac1-Nox2 pathway (NSC23766) significantly attenuates hyperglycemia-induced p38 MAP kinase in the retina and its capillary cells and [ii] 2-BP, an irreversible inhibitor of S-acyltransferase, markedly attenuates Rac1-Nox2-p38 MAP kinase cascade." (PMID 25967961, 2015).
Hypertension (28 papers, 2015 to 2026). The presence of chronic increased pressure in the systemic arterial system. "As an intracellular signalling molecule activated by extracellular stimuli, RAC1 not only is implicated in the pathogenesis of cardiac hypertrophy and hypertension but also regulates bronchoconstriction." (PMID 36018772, 2022). "The involvement of Nox and Rac1/2 in hypertension-associated hypercontractility was assessed by pre-incubating vessels with the Rac1/2 inhibitor, EHT1864 or the Nox1 inhibitor, ML171." (PMID 28478264, 2017). "Rather, hypertensive effects could be expected, as Rac1 knockout in mice was associated with hypertension, due to increased vascular resistance resulting from disruption of nitric oxide-induced vasorelaxation." (PMID 32317972, 2020). "Considering that CYBA variants have been widely studied in cardiovascular diseases, including coronary heart disease and hypertension, which are tightly associated with increased levels of ROS, RAC1 rs10951982 may also play a part in inducing oxidative stress." (PMID 29342889, 2018). "Variant rs10951982 in RAC1 has been implied in the increased risk of hypertension." (PMID 29342889, 2018). "And according to the previous observations, it has been proposed that alterations of Rac1 could influence susceptibility to diseases such as hypertension or renal failure by impairing the correlated proteins or altering the activity or expression of Rac1." (PMID 26841219, 2016). "It is reasonable to speculate that RAC1 gene might be implicated in hypertension or ERSD." (PMID 26841219, 2016). "Meanwhile, we emphasize the importance of cardiac metabolic remodeling and Rac1 in inducing and reversing left atrial remodeling at the early stage of hypertension." (PMID 36324689, 2022). "In salt-sensitive rodent hypertension models, high-salt loading activates Rac1 in the kidneys, leading to blood pressure elevation and renal injury, presenting as severe proteinuria and extensive podocyte damage." (PMID 33343355, 2020). "Normotensive FHL2 KO mice have unchanged baseline Rac1 activity, but the upregulation of GTP-Rac1 level was significantly suppressed in hypertension compared to their hypertensive WT littermates." (PMID 31040292, 2019). "Since in vitro experiments suggest FHL2 facilitate FAK activity to turn-on Rac1 in hypertensive podocytopathy, we therefore isolated glomeruli from the four groups of mice to analyze Rac1 activity in vivo." (PMID 31040292, 2019). "Overexpression of Rac1 in smooth muscle cells in mice induces hypertension as it regulates the redox state of the blood vessels and blood pressure homeostasis through the NADPH oxidase pathway." (PMID 28157227, 2017). "Moreover, it has been demonstrated that SNPs rs836478 (C/T) and rs10951982 (G/A) in RAC1 gene were associated with higher level of biomarkers (interleukin 6, metalloproteinase-9, and plasminogen activator inhibitor-1) related to the development and progression of hypertension." (PMID 26841219, 2016). "Rac1 knockout has been shown to inhibit EC migration and tubulogenesis, and mice with endothelial Rac1 haploinsufficiency display mild hypertension that appears to be a result of insufficient endothelial nitric oxide synthase (eNOS) activity." (PMID 26436659, 2015). "In their study, a high-salt intake acted synergistically with aldosterone to activate renal Rac1 in salt-sensitive hypertension loading, resulting in high blood pressure and renal damage through potentiating mineralocorticoid receptors." (PMID 26109460, 2015). "Smooth muscle‐specific overexpression of constitutively active Rac1 induced moderate hypertension." (PMID 41252219, 2025). "Therefore, we concluded that high salt intake probably provokes PKC γ/Rac1/NAD(P)H pathway-dependent oxidative stress by regulating NKA α2 levels in the PVN during salt-induced hypertension development." (PMID 35204171, 2022).